RN7SKP29 (RN7SK pseudogene 29)
Gene: Miscellaneous RNA gene on chromosome 8 (69,700,224 to 69,700,495, forward strand). Ensembl gene ENSG00000222889.
Homologues: Orthologues: chimpanzee 7SK (99% identical). Paralogues in human: RN7SKP255 (75% identical), RN7SKP180 (73% identical), RN7SKP75 (73% identical), RN7SKP9 (72% identical), RN7SKP90 (71% identical), RN7SKP128 (71% identical), RN7SKP189 (71% identical), RN7SKP217 (71% identical), RN7SKP28 (71% identical), RN7SKP211 (70% identical), RN7SKP250 (70% identical), RN7SKP37 (70% identical), and 284 more.